MRPL50 (mitochondrial ribosomal protein L50)
Synonyms: MRP-L50; FLJ20493; mL50
Tractability: Small molecule: a structure with a bound ligand is known. PROTAC: ubiquitination databases record sites on it; its protein half-life has been measured.
Gene: Protein-coding gene on chromosome 9 (101,387,633 to 101,398,618, reverse strand). Ensembl gene ENSG00000136897.
Subcellular location: Mitochondrion
Subcellular location (Human Protein Atlas): Mitochondria; Cytosol
Pathways (Reactome):
Metabolism of proteins: Mitochondrial ribosome-associated quality control; Mitochondrial translation elongation; Mitochondrial translation initiation; Mitochondrial translation termination
Gene Ontology:
Biological process: mitochondrial translation
Cellular component: mitochondrial large ribosomal subunit; mitochondrion; mitochondrial inner membrane
Genetic constraint (gnomAD): Loss-of-function variants: 10 observed, 15.66 expected, observed/expected ratio (o/e) 0.64, 90% interval 0.39 to 1.08. The upper end of that interval is the gene's LOEUF score, 1.08, which puts it in group 4 of 6, group 1 being the genes least tolerant of losing a copy. Missense variants: 213 observed, 194.87 expected, observed/expected ratio (o/e) 1.09, 90% interval 0.98 to 1.22. Synonymous variants: 68 observed, 69.86 expected, observed/expected ratio (o/e) 0.97, 90% interval 0.8 to 1.19.
Homologues: Orthologues: chimpanzee MRPL50 (98% identical), macaque MRPL50 (96% identical), pig MRPL50 (80% identical), dog MRPL50 (78% identical), mouse Mrpl50 (78% identical), guinea pig MRPL50 (77% identical), rabbit MRPL50 (73% identical), rat Mrpl50 (72% identical), Drosophila melanogaster mRpL50 (26% identical), Caenorhabditis elegans mrpl-50 (21% identical).
Diseases named in the same sentence as MRPL50 in open-access papers:
MRPL50 is named in the same sentence as 9 diseases in open-access papers, as found by Europe PMC text mining. Sharing a sentence is not in itself a finding about the gene and the disease. The quoted sentences say what the papers report.
chronic kidney disease (1 paper, 2023). Impairment of the renal function secondary to chronic kidney damage persisting for three or more months. "Here we present data to support MRPL50 deficiency as a novel cause of a mitochondrial disorder, manifesting with premature ovarian insufficiency, sensorineural hearing loss and chronic kidney disease in dizygotic twin sisters." (PMID 37148394, 2023).
glaucoma (1 paper, 2023). Increased pressure in the eyeball due to obstruction of the outflow of aqueous humor. "Both MRPL50 and NDUFB3 have been implicated in AD, glaucoma, and age-related neurodegeneration." (PMID 37834458, 2023).
Infertility (1 paper, 2023). "This is highlighted by MRPL50-deficient Drosophila models showing abnormal ovarian structure and having subsequent infertility." (PMID 37148394, 2023). "MRPL50 could therefore be considered a candidate gene underlying male infertility, consistent with many known POI genes that can cause infertility of both sexes (e.g. STAG3, ZSWIM7, etc.)." (PMID 37148394, 2023).
pancreatic tumor (1 paper, 2023). "However, the role of COQ4, MCRIP2, MRPL50, MRPL14, RFK, and NMNAT3 in pancreatic tumor has not been reported." (PMID 37223030, 2023).
infection (1 paper, 2019). The state of being infected such as from the introduction of a foreign agent such as serum, vaccine, antigenic substance or organism. "For host interactions, MRPL50 via C. albicans WO-1 infection directly triggers TF FOXA1 but not protein MYC (also knowns C-Myc) in C. albicans SC5314 infection." (PMID 30769958, 2019).
mitochondrial disease (1 paper, 2023). "Identifying MRPL50 as a mitochondrial disease gene associated with POI adds to growing evidence that the mitochondrial ribosome is critical for ovarian function and fertility." (PMID 37148394, 2023). "In conclusion, here we provide the first evidence of bi-allelic variants in MRPL50 as a cause of mitochondrial disease." (PMID 37148394, 2023).
MRPL50 also shares sentences with these, for which no sentence is quoted: male infertility (1 paper); Perrault syndrome (1); Premature ovarian insufficiency (1).